TMEM38B (transmembrane protein 38B)
Description:
Intracellular monovalent cation channel required for maintenance of rapid intracellular calcium release. Acts as a potassium counter-ion channel that functions in synchronization with calcium release from intracellular stores (By similarity). Activated by increased cytosolic Ca(2+) levels (By similarity).
Synonyms: TRIC-B; TRICB; C9orf87; FLJ10493; bA219P18.1; D4Ertd89e; OI14
Tractability: Antibody: UniProt predicts a signal peptide or a membrane-spanning region. PROTAC: ubiquitination databases record sites on it.
Gene: Protein-coding gene on chromosome 9 (105,694,519 to 105,776,629, forward strand). Ensembl gene ENSG00000095209.
Subcellular location: Endoplasmic reticulum membrane
Gene Ontology:
Molecular function: protein binding; potassium channel activity; identical protein binding
Biological process: potassium ion transmembrane transport; regulation of release of sequestered calcium ion into cytosol; release of sequestered calcium ion into cytosol by sarcoplasmic reticulum
Cellular component: nucleus; endoplasmic reticulum; endoplasmic reticulum membrane; nuclear membrane; sarcoplasmic reticulum membrane; membrane
Genetic constraint (gnomAD): Loss-of-function variants: 20 observed, 21.86 expected, observed/expected ratio (o/e) 0.91, 90% interval 0.64 to 1.33. The upper end of that interval is the gene's LOEUF score, 1.33, which puts it in group 5 of 6, group 1 being the genes least tolerant of losing a copy. Missense variants: 344 observed, 337.21 expected, observed/expected ratio (o/e) 1.02, 90% interval 0.93 to 1.12. Synonymous variants: 124 observed, 127.22 expected, observed/expected ratio (o/e) 0.97, 90% interval 0.84 to 1.13.
Homologues: Orthologues: macaque TMEM38B (98% identical), chimpanzee TMEM38B (95% identical), pig TMEM38B (87% identical), dog TMEM38B (85% identical), guinea pig TMEM38B (80% identical), rat Tmem38b (75% identical), mouse Tmem38b (73% identical), tropical clawed frog tmem38b (51% identical), Drosophila melanogaster CG4239 (33% identical), Caenorhabditis elegans tric-1B.1 (31% identical), Caenorhabditis elegans tric-1B.2 (31% identical). Paralogues in human: TMEM38A (41% identical).
Diseases named in the same sentence as TMEM38B in open-access papers:
TMEM38B is named in the same sentence as 28 diseases in open-access papers, as found by Europe PMC text mining. Sharing a sentence is not in itself a finding about the gene and the disease. The quoted sentences say what the papers report.
osteogenesis imperfecta (19 papers, 2016 to 2025). Osteogenesis imperfecta (OI) comprises a heterogeneous group of genetic disorders characterized by increased bone fragility, low bone mass, and susceptibility to bone fractures with variable severity. "Osteogenesis imperfecta (OI) type XIV is a rare recessive disorder caused by TMEM38B pathogenic variants that disrupt an endoplasmic reticulum protein essential for calcium homeostasis and bone mineralization." (PMID 41465594, 2025). "In our study, we report a case of TMEM38B-associated autosomal recessive osteogenesis imperfecta in a child of a consanguineous family presented with a history of multiple prenatal and postnatal fractures." (PMID 39385871, 2024). "The genetic diagnosis of the autosomal recessive osteogenesis imperfecta type XIV is confirmed by detecting a 22-kb homozygous loss on 9q31.2 encompassing the TMEM38B gene." (PMID 34036147, 2021). "Truncating biallelic variants in the TMEM38B gene are an established mechanism causing autosomal recessive osteogenesis imperfecta type XIV (MIM 615066)." (PMID 34627339, 2021). "This study strengthens the fact that abnormal bone development is associated with TMEM38B deficiency leading to autosomal recessive osteogenesis imperfecta in humans and further helps us to elucidate the pathogenesis of TMEM38B pathogenic variants." (PMID 34036147, 2021). "Mutations in TMEM38B were connected to osteogenesis imperfecta, and skeletal problems are common in MPS." (PMID 32886284, 2020). "Mutations in TMEM38B cause one subtype of osteogenesis imperfecta, which can include SkM and cardiac deficiencies." (PMID 34968235, 2020). "Pathogenic variations in TMEM38B were reported to cause a rare autosomal recessive type of osteogenesis imperfecta (OIXIV, MIM #615066)." (PMID 31218223, 2019). "Genetic mutations of the human TMEM38B gene (encoding the TRIC-B protein) are found in patients with a hereditary brittle bone disease called osteogenesis imperfecta." (PMID 28431535, 2017). "Why do null mutations for TMEM38B cause osteogenesis imperfecta, which is a collagen-related condition?" (PMID 27441836, 2016). "Osteogenesis imperfecta cases in our region have significant genetic heterogeneity and this additional case highlights the contribution of TMEM38B Bedouins’ founder mutation to the genetic landscape of autosomal recessive osteogenesis imperfecta in our population." (PMID 34036147, 2021). "Serious mutations in the TRIC-B (also referred to as TMEM38B) locus cause autosomal recessive osteogenesis imperfecta (OI), which is characterized by insufficient bone mineralization." (PMID 38123563, 2023). "A skeletal phenotype is similarly described in humans with loss of function mutations in TMEM38B, which are affected by a recessive form of osteogenesis imperfecta (OI), classified as OI type XIV (OMIM 615066)." (PMID 36755921, 2023). "Mutations in TMEM38B, encoding TRIC‐B, impair the rER Ca2+ flux and cause the recessive osteogenesis imperfecta (OI) type XIV (OMIM #615066)." (PMID 39834042, 2025). "In 2014, the identification of TMEM38B loss-of-function mutations in individuals affected by the recessive form of osteogenesis imperfecta (OI) type XIV demonstrated an unexpected and relevant role for the ER ion channel TRIC-B in mammalian bone homeostasis." (PMID 36755921, 2023).
osteogenesis imperfecta (continued). "The skeletal phenotype described in osteogenesis imperfecta (OI) type XIV, and caused by TMEM38B loss-of-function mutations in mammals, demonstrated a relevant role of TRIC-B in bone homeostasis." (PMID 36755921, 2023). "A study of multiplex consanguineous families and simplex cases identified a homozygous deletion of TMEM38B exon 4 in three Saudi families with a moderately severe bone phenotype characterized as osteogenesis imperfecta type XIV (MIM# 615066)." (PMID 34036147, 2021). "OI type XIV is a rare form of osteogenesis imperfecta caused by defects in the trimeric intracellular potassium channel B (TRIC-B), an integral membrane protein encoded by tmem38b, necessary for the regulation of Calcium flux across the endoplasmic reticulum membrane." (PMID 39320469, 2024). "The role of encoded TRIC-B in intracellular Ca2+ homeostasis and Ca2+ flux kinetics in the endoplasmic reticulum supports that the absence of TMEM38B is associated with osteogenesis imperfecta due to dysregulation of collagen biosynthesis." (PMID 34036147, 2021).
respiratory failure (2 papers, 2023 to 2025). The significant impairment of gas exchange within the lungs resulting in hypoxia, hypercarbia, or both, to the extent that organ tissue perfusion is severely compromised. "A global knockout mouse model for Tmem38b (Tmem38b−/−) was generated, but unfortunately Tmem38b−/− mice died shortly after birth because of respiratory failure." (PMID 39834042, 2025). "Mutations in TMEM38B are associated with pulmonary dysfunction both in OI type XIV individuals and in the Tric-B knock out mouse model, which dies immediately after birth due to respiratory failure." (PMID 36755921, 2023).
ocular melanoma (1 paper, 2025). A melanoma that arises from the structures of the eye or ocular adnexa. "In ocular melanoma, BACE2 has been found to mediate intracellular calcium release from the endoplasmic reticulum and support tumor progression by regulating the expression of TMEM38B, a cation channel protein in the endoplasmic reticulum membrane." (PMID 39981249, 2025).
tumor (5 papers, 2020 to 2025). "BACE2 regulated ER calcium release by influencing the expression of transmembrane protein 38B (TMEM38B), which in turn promoted the proliferation and migration of tumor cells." (PMID 41315216, 2025). "Subsequently, TMEM genes expression of stromal cells in normal and tumor tissues was compared, and TMEM158, TMEM38B, VMP1 and TMEM45A were recognized as DEGs." (PMID 37265785, 2023). "Frozen tumor tissues and plasma were used to measure PBRM1, BAP1, SET domain-containing 2 (SETD2), KDM5C, FOXC2, CLIP4, AQP1, DDX11, BAIAP2L1, and TMEM38B mRNA levels, and correlation with the Fuhrman grade was investigated." (PMID 32392781, 2020). "Furthermore, we suggest that the dynamic change of ANO1, TMEM38B, TMEM158, and TMEM45A may indicate stellate cell activation and trigger tumor stromal remodeling." (PMID 37265785, 2023).
cancer (2 papers, 2020). A tumor composed of atypical neoplastic, often pleomorphic cells that invade other tissues. "For RFS, those with cancer recurrence presented higher expression patterns of DDX11 and lower expressions of TMEM38B and PRUNE2, in both the univariate and multivariate analyses." (PMID 31963294, 2020). "For CSS, patients with cancer-specific death presented higher expression patterns of RGPD8, BAIAP2L1, and DDX11 and lower expression patterns of SLC16A9, FRAS1, AQP1, TMEM38B, and PRUNE2, in both the univariate and multivariate analyses." (PMID 31963294, 2020). "Patients who had DDX11-positive and TMEM38B-negative tumors had significantly higher chances of cancer-specific death (odds ratio [OR] 49.000; 95% confidence interval [CI] 3.765–637.794) and recurrence (OR 28.000, 95% CI 2.399–326.735)." (PMID 31963294, 2020).
skeletal dysplasia (2 papers, 2018 to 2025). Any Mendelian diseases that affects growth and development of the skeleton. "In 2024, genetic analysis using a next-generation sequencing (NGS) panel specific to skeletal dysplasias identified a homozygous variant in TMEM38B (NM_018112.3:c.112 + 1G > T), classified as likely pathogenic and consistent with autosomal recessive OI Type XIV." (PMID 41465594, 2025). "This included seven genes (LIFR, TMEM38B, PLS3, NANS, SLC26A2, ALX4, and PLS3) associated with skeletal dysplasia or bone disease, and four of them were ARE-containing genes with increased expression." (PMID 29727687, 2018).
TMEM38B also shares sentences with these, for which no sentence is quoted: atrial septal defect (1 paper); Bruck syndrome (1); cardiac arrest (1); cardiac disease (1); cyst (1); deficiencies (1); developmental delay (1); glaucoma (1); heart failure (1); Hurler syndrome (1); Kidney Cyst (1); myotonic dystrophy type 1 (1); Neurological disorders (1); osteoarthritis (1); Osteogenesis (1); osteoporosis (1); phospholipidosis (1); polycystic kidney disease (1); polycythemia (1); scoliosis (1); skeletal disease (1); Treacher-Collins syndrome (1).